SOX9 (SRY-box transcription factor 9)
Diseases named in the same sentence as SOX9 in open-access papers (continued):
Sharing a sentence is not in itself a finding about the gene and the disease.
tumor (continued). "The hormone-dependent inhibition of Sox9 is in agreement with our previous reports on the effects of estrogen contributing to a more differentiated phenotype by reducing the stem cell pool in the human breast and the association between high CSC content and poorly differentiated tumours." (PMID 30622340, 2019). "Besides, a truncated version of SOX9 devoid of transactivation domain as a result of retention of the second intron called MiniSOX9 has been discovered in human tumor samples of CRC; this version is expressed at high levels in CRC but it is undetectable in the surrounding healthy tissue." (PMID 31057614, 2019). "In this regard, ST6Gal-I knockdown decreased the levels of SOX9, suggesting that SOX9 expression was regulated by a specific glycosyltransferase, and tumor glycosylation could be a mechanism for functionally shifting cells to a less differentiated, stem-like state." (PMID 31057614, 2019). "On the one hand we could not find any association between SOX9 expression and tumour stage nor age which is in line with others." (PMID 29121666, 2017). "Furthermore, qRT-PCR analysis showed that SOX9 was obviously down-regulated in miR-101-U87 tumor compared with the miR-NC-U87 tumor in tumor xenograft model, indicating that SOX9 might be a potential target gene of miR-101." (PMID 27911279, 2017). "Therefore, therapeutic strategies targeting SOX9 and it ́s up-stream effectors might be helpful in treating SOX9-dependent tumours." (PMID 29121666, 2017). "In contrast, Sox9 was detectable in all tumours with a significantly higher expression in aCP compared to pCP (protein, p < 0.0001; mRNA p = 0.0484) This was also true for the respective tumour adjacent CNS where 63 aCP (98.4%) and six pCP (66.7%) showed Sox9+ cells." (PMID 29158570, 2017). "Furthermore, statistical analyses showed that SOX9 expression was positively correlated with tumor clinical stage (P < 0.001), T classification (P = 0.001), N classification (P < 0.001), M classification (P = 0.006), and pathological differentiation (P = 0.017)." (PMID 26384302, 2015). "Furthermore, the tumor xenografts formed by HeLa-shSOX9 cells grew much faster than tumors formed by the control cells (HeLa-shGFP cells) (p <0.01) because HeLa cells express high levels of endogenous SOX9 protein." (PMID 26036262, 2015). "In KRAS-mutant lung ADCs, Sox9 overexpression may be secondary event associated with tumor progression, rather than directly downstream of the Kras pathway." (PMID 25004243, 2014). "Spatial transcriptomics revealed distinct expression patterns of SOX9 and TIMP1 within tumor tissues, supporting the conclusion that SOX9 transcriptionally activates TIMP1 to suppress DC maturation." (PMID 41270217, 2026). "siRNA-based RNAi, for example, excels in sequence-specific SOX silencing, with preclinical NSCLC models showing decreased tumor growth and stemness following SOX2 or SOX9 knockdown." (PMID 41268614, 2026). "SOX9 KO in both GA0518 and AGS cells led to significantly decreased LIF transcription and secretion; LIF and SOX9 were co‐expressed in tumor cells, and LIF was elevated in malignant ascites but undetectable in plasma and cytology‐negative peritoneal washings." (PMID 41163398, 2025). "Subsequently, we intervened in CRC cells with SOX9‐KO using CMD‐BHQ3‐PTL/DOX@RBCm and assessed stemness in tumor cells using WB, immunofluorescence experiments, and correlation analysis." (PMID 39523731, 2025). "The expansion of proliferating SOX9-expressing stem cells occurs following inducible depletion of α-catenin in HFSCs, culminating in SCC tumor development in vivo." (PMID 40399946, 2025). "Previous studies have shown that SOX9 can be ubiquitinated by the E3 ligases KEAP1 or FBXW7, leading to its proteasomal degradation and consequent suppression of tumor progression." (PMID 41428171, 2025).
tumor (continued). "Consistently, biomarkers associated with cell dormancy as well as stemness were upregulated in tumor cells expressing high levels of TRAF4; however, their expression, including DEC2, SOX9, NR2F1, and P27, declined in cells expressingTRAFA‐P12A." (PMID 39716976, 2025). "Subsequently, we investigated the reciprocal interaction between SOX9 and YAP1 at both cellular and tumor tissue levels, employing immunoprecipitation (IP) experiments." (PMID 39523731, 2025). "Next, to demonstrate the selective differentiation-inducing effect of VPA in tumor cells, we evaluated the expression of the CSC markers Sox9, Axin2, Cd44, and Ascl2 in organoids isolated from healthy mouse intestines." (PMID 40750758, 2025). "By directly upregulating B7-H4 via STAT3 signaling, SOX9 reduces CD8+ T cell infiltration while increasing Tregs, effectively shutting down anti-tumor immunity." (PMID 41293317, 2025). "Inducing Prox1 OE after 21 days of HDTVI-mediated tumor formation also decreased glandular structures and reduced cholangiocyte marker expression (KRT19 and SOX9)." (PMID 39948437, 2025). "Western blot data suggest that the expression of Sox9 and Snail M13HS-2 and M13HS-8 tumor hybrids treated with minocycline was likely reduced." (PMID 40471394, 2025). "Next, using CRISPR/Cas9 technology to knockout Olig1/2, we found that astrocyte differentiation markers such as GFAP, SOX9, and HOPX were preserved, but tumor cell proliferation was significantly diminished." (PMID 40428395, 2025). "In line with our previous findings, tumor areas showed strong nuclear staining for TFE3, TFEB, and SOX9." (PMID 40189703, 2025). "Four phenotypes characterized by expression of CD44 and CD133 (ALDH1/CD44/CD133, CD44, CD44/SOX9 and CD44/CD133) were more prevalent in grade 1 tumor biopsies." (PMID 39888143, 2025). "Immunohistochemical staining revealed that GFP+ tumor cells in both control and Olig1/2F/+; H2bF/+ groups exhibited robust expression of astrocytic markers, including GFAP and SOX9." (PMID 40428395, 2025). "The expression of SOX12 was higher in the tumor cell subgroup compared to normal subgroup, whereas other SOX transcripts, including SOX2, SOX5, SOX9, SOX11, and SOX15, had low expression in tumor clusters." (PMID 40593465, 2025). "Bulk RNA‐seq and single‐cell RNA‐seq of 37 PC specimens revealed enrichment and positive correlation of SOX9, LIF, LIFR, and IL6ST (GP130) in tumor cells." (PMID 41163398, 2025). "We found that CSCs expressed high levels of tumor stemness genes (PROM1, CD24, CD47, ANPEP, ALDH1A1, OLFM4, and SOX9), and demonstrated a high cancer stemness score, along with activation of the cancer driver genes EGFR and ERBB2." (PMID 39950944, 2025). "In vitro experiments showed that compared with 2D GC cell culture, the expression of ONECUT2 protein and stemness-related markers CD44, SOX9, SOX2, and LGR4 simultaneously increased in 3D tumor stem cell spheroid culture." (PMID 38997271, 2024). "The difference in SOX2/SOX9 expression and WNT signaling silencing enables tumor cells to enter a quiescent state and to evade the immune clearance by natural killer (NK) cells, finally resulting in propagation into metastasis-establishing cells." (PMID 38275880, 2024). "Taken together, SOX9 and TCF7L2 formed a transcriptional co‐dependent circuit and were indispensable for maintaining tumor malignancy of GBC in vitro and in vivo." (PMID 39492805, 2024). "Here, we demonstrated that INHBA expression is highly expressed after a fractionated dose of radiation in all tumor cells, while SERPINE1 expression was highly increased in the cells with knockdown of SOX9 after irradiation." (PMID 38275880, 2024).
tumor (continued). "Stable LIN28B downregulation resulted in a significant decrease in the tumor markers SOX2, NESTIN, and SOX9 and an increase in the neural differentiation marker GAP43, consistent with the critical role of LIN28B in maintaining stemness." (PMID 38732012, 2024). "In TCGA-HNSCC, clinical characteristics were found to differ between groups with opposite expression levels of SOX2 and SOX9, with significance observed for gender, HPV status, tumor location, and radiation treatment." (PMID 38275880, 2024). "SOX9 gene knockout and apyrase (an ATP hydrolase) treatment of MDA-MB-231 cells showed inhibition of tumor growth and increase of drug sensitivity in nude mice." (PMID 39738256, 2024). "In conclusion, these findings indicated that the expression of SOX9 and TCF7L2 can delineate clinically meaningful tumor subgroups." (PMID 39492805, 2024). "Akt and YAP1 plasmids were co-delivered by SB-HDTVI into Alb-Cre;Sox9flox/flox (Sox9 LKO) or Sox9flox/flox (LWT) in which Sox9 was deleted HC and BEC initiated at around day E15, resulting in chronic developmental deletion prior to tumor formation." (PMID 39273023, 2024). "Inducible silencing of either SOX9 or TCF7L2 potently increased apoptosis and decreased proliferation, resulting in suppression of tumor growth of the SOX9‐TCF7L2 double‐high GBC model in vivo." (PMID 39492805, 2024). "Since Sox9 deletion decreases survival in Akt-YAP1 mice with a larger tumor burden, we next sought to evaluate tumor cell death and proliferation through histologic observation." (PMID 39273023, 2024). "Cell survival, tumor sphere formation and the SOX2 and SOX9 expression were analyzed in the cells silenced for SOX2 or SOX9 and compared to control cell lines." (PMID 38275880, 2024). "This peptide effectively disrupts the SOX9-YAP interaction, preventing the nuclear localization and oncogenic function of YAP, and exhibiting significant therapeutic effects in mouse tumor models." (PMID 38653754, 2024). "We found that SOX9 negatively correlated with CD8+ T cells, activated NK cells, M2 macrophages, and other tumor-infiltrating immune cells." (PMID 37020558, 2023). "In line with studies from others, in our mouse model, the CCA tumor component within the cHCC-CCA tumors from the HE and HO mice stained positive for the progenitor markers SOX9 and EpCAM." (PMID 37627221, 2023). "The expression levels of SOX9 and RAP1 in tumor tissues and A549 cells of LUAD patients were significantly increased and positively correlated." (PMID 37919693, 2023). "As expected, OPC markers OLIG2, SOX9, and cell cycle genes CDK1, MKI67 are highest in the tumor core (early peak), while neuronal markers ZIC1, GABRA1, and mature oligodendrocyte marker MBP are highest in the GCL_N (late peak)." (PMID 36823172, 2023). "In the breast cancer model, ATP mediates IL-6 release and activates JAK1-STAT3 signaling via P2Y2 receptors, upregulating SOX9 and its target gene CEACAM5/6, which is involved in tumor invasion." (PMID 36750864, 2023). "In an analysis of the anti-tumour mechanism, AT-101 showed a strong inhibitory effect on YAP1 in the Hippo signalling pathway and SOX9 (SRY-Box Transcription Factor 9)." (PMID 38098026, 2023). "This XIST-driven production of IL-6 from ALDH− bulk tumor cells preferentially binds to IL6R on ALDH+ CSCs to drive STAT3 activation and expression of key CSC factors (i.e., c-MYC, KLF4 and SOX9), promoting self-renewal of ALDH+ CSCs." (PMID 36922677, 2023). "Tumor sections were excised from FFPE by macrodissection, RNA was extracted and SOX9 mRNA and miR-138 were quantified via quantitative PCR." (PMID 38002064, 2023). "The impact of SOX9 and JMJD1C depletion on OS tumor growth was examined in vivo using xenografts and immunohistochemistry." (PMID 37491298, 2023).
tumor (continued). "We also verified the positive correlation between ID1 expression and SOX9 (p = 6.90e‐05, r = 0.20), EPCAM (p = 5.37e‐06, r = 0.23), CD24 (p = 1.82e‐07, r = 0.27), and CLDN4 (p = 6.04e‐05, r = 0.18) expression in HCC tumor tissue from TCGA datasets." (PMID 37085918, 2023). "RT-qPCR was applied to observe the expression of SOX9 and RAP1 in tumor tissues and corresponding normal lung tissues collected from LUAD patients." (PMID 37919693, 2023). "Multivariable linear regression was performed to ascertain the possible relation between distance from tumor centroid to SVZ and age, sex, and percentage of positive core cells of SOX2, SOX9, Nestin, and Ki67." (PMID 35795469, 2022). "Lung tissue from EM and SM models, primary tumor tissues, and CTCs from the SM model were stained for GFP, NR2F1, SOX9, and DAPI." (PMID 35110548, 2022). "By giving tumor cells the ability to evade NK cells, SOX2 and SOX9 have been found to promote the immune evasion of tumor cells." (PMID 36524115, 2022). "Strikingly, markers of normal colon stem cells (LGR5, ASCL2, SOX9), were also strongly downregulated EHFlow CRC cells, suggesting that these lines give rise to tumours that are de-differentiated to the point of losing their colonic identity." (PMID 35606410, 2022). "Nevertheless, substantial studies demonstrated that SOX9 is overexpressed in HCC tissues and is closely related to poor differentiation, venous invasion, high tumor stage, and worse survival of patients with HCC." (PMID 35267473, 2022). "Here, we expand this work with the finding that the primary tumor induces the expression of both NR2F1 and SOX9 in disseminating tumor cells that are in the vicinity of TMEM doorways." (PMID 35110548, 2022). "Consistently, SOX9 and SMAD2 were significantly elevated in tumor cells from the diversity-high group." (PMID 35322024, 2022). "We first compared the ratio of SOX9/MKI67-positive cells in normal and tumor tissues in vivo and primary tumor-derived organoid in vitro." (PMID 35974387, 2022). "To further analyze the correlation between expression of cell markers (SOX2, SOX9, Nestin, and Ki67) and the proximity to the SVZ, we used the distance from centroid of tumor to SVZ." (PMID 35795469, 2022). "SOX9 is a critical downstream effector of ERG in TMPRSS2-ERG-positive cancer cells and induces neoplasia and tumor invasion when overexpressed in the murine prostate or cancer cells, respectively, similarly to ERG." (PMID 35267426, 2022). "Tissue microarrays of tumor samples for patients between 2007 and 2016 were used for immunodetection of Nestin, SOX2, SOX9, KLF4, NANOG, CD133 cMYC, and Ki67." (PMID 35795469, 2022). "We investigated SOX9 protein levels in the same 33 pairs of human CRC tumors and matched mucosa, 2 tumor samples were omitted due to protein degradation observed in ACTB NI‐WB." (PMID 34919787, 2022). "Tumors displayed an undifferentiated morphology, were positive for the NB marker PHOX2B, and maintained high amounts of MES markers SOX9 and LGR5 along with low ADR marker TH, in concordance with the parental relapse tumor." (PMID 36306349, 2022). "Thus, it would be important to evaluate whether SOX9 silencing by SOX9-specific shRNA or anti-sense oligonucleotide (ASO), which can inhibit SOX9 mRNA stability or SOX9 protein translation, is able to reduce tumor growth and metastasis in a xenograft mouse model harboring preformed tumors." (PMID 35159173, 2022). "SOX9 is an HMG-box transcription factor in the SOX family of proteins, and it plays a key role in tumor development and progression, including tumor initiation, TME regulation, metastasis, and drug resistance." (PMID 36551568, 2022).
tumor (continued). "Our studies have uncovered Sox9 as a novel substrate for AKT, providing a novel link between AKT and tumor progression." (PMID 33985544, 2021). "Previous reports on the role of SOX9 in CRC have yielded mixed results, such as a tumor suppressor and having oncogenic functions." (PMID 34568045, 2021). "Immunohistochemistry staining showed that SOX9 was highly expressed in the nuclei of the epithelial cells of the Hassall’s corpuscles and of the TET tumor cells." (PMID 34778027, 2021). "Large areas of intense staining of SOX1, SOX9 and MAP2 suggested that cells with neural stemness and neuronal features were among the major cell types in tumor." (PMID 33468253, 2021). "This was further supported by Western blot analyses on infigratinib‐resistant tumours, where there was an increase in CSC markers such as SOX9, YAP1 and DLK1 particularly in the later stages of resistance." (PMID 33179425, 2021). "In HCC cell lines ectopically expressing Sox9-eGFP (SOX9 promoter driven enhanced green fluorescent protein), FACS-isolated SOX9+ cells are found to be the tumor forming cells." (PMID 34083580, 2021). "Our data show that AKT can directly phosphorylate Sox9 in vitro at serine 181 and that AKT inhibition blocks Sox9 phosphorylation and Sox10 expression in SLK(-/-) tumor cells." (PMID 33985544, 2021). "Based on genomic datasets, the expression profiles of candidate genes in CCA cases were analyzed using GEO databases and the increasing levels of feasible tumor markers including HMGB1, SOX9, and YAP1 in patients with CCA." (PMID 35201494, 2021). "SOX9 is a part of the SRY-related gene family, closely related to tumor development and progression." (PMID 34556140, 2021). "To establish a potential link with active Sox9 in Sox10+ human samples, we assessed the levels of pSox9 S181 and Sox10 by immunohistochemistry across HER2-positive, luminal, and TNBC tumor cores." (PMID 33985544, 2021). "Exosomal miR-140 downregulated the SRY-Box transcription factor 9 (SOX9) in Ductal Carcinoma In situ cells (DCIS), interfering with tumor growth, survival, and invasion." (PMID 31952362, 2020). "As expected, tumor sphere formation assays determined that circPTN promoted increased levels of stemness markers, such as Nestin, CD133, SOX2, and SOX9, and tumor growth in vitro and in vivo, primarily via sponging miR-145-5p/miR-330-5p." (PMID 32528957, 2020). "Both normal and tumor human-derived pancreatic organoids expressed lineage markers of the pancreas including HNF-1β, CK19 and SOX9." (PMID 33348809, 2020). "In the present work, we confirmed the close similarities between TB tumor cells and epithelial MC progenitors, evident by expression of GLI1 and its related downstream targets, i.e., KRT17 and SOX9, in both settings." (PMID 32708246, 2020). "To further explore the impact of SOX9 on CRC cell stemness, we conducted secondary and tertiary tumor sphere-formation assays." (PMID 33318478, 2020). "Expressions of CD90, EpCAM, CD133, CD24, SOX9, CD44, CK19, and CD47 were positively related to immune infiltration level in HCC, negatively related to tumor purity." (PMID 32184801, 2020). "Tumor-suppressive miR-34c was often downregulated in various types of tumor cells and regulated EMT through direct binding with SOX9, SATB2, MAP3K2, and DANCR mRNA." (PMID 32252322, 2020). "For instance, SOX9 overexpression was commonly observed in those HCC high tumor stage and tumor grade tissues." (PMID 31057614, 2019). "After establishing a stable overexpression system of mimic miR-330-5p through the lentiviral transfection of G15 cells, we performed a tumor sphere formation assay and measured the expression of stemness markers (Nestin, CD133, SOX9, and SOX2)." (PMID 31511040, 2019). "To further investigate the correlation between SOX9 and COL10A1 expression in vivo, we performed QPCR and western blot analysis using 30 pairs of tumor tissues (T) and adjacent normal gastric mucosa (N)." (PMID 30154451, 2018).